RAC1 (Rac family small GTPase 1)
Diseases named in the same sentence as RAC1 in open-access papers (continued):
Sharing a sentence is not in itself a finding about the gene and the disease.
cancer (continued). "Inhibition of ERK activity by U0126 or suppression of Rac1 activity by ectopic expression of inactive mutant form of Rac1 (Rac1-T17N) significantly prevents EGF-induced cell migration, suggesting that EGF-induced ERK and Rac1 activation was responsible for the migration of these cancer cells." (PMID 22701712, 2012). "Although it is not desirable to fully activate RAC1 in every tissue due to its role as a known cancer-driving oncogenic factor, temporal and tissue-specific modulation of active RAC1 may be beneficial for rescuing some of the DOCK3-affected pathways that are altered in patients." (PMID 37895289, 2023). "While the impact of hypomethylation at cg18447419 on the action of AHR-mediated RhoA/Rac1 signaling is unknown, this CpG and SLC9A3 should be considered in future candidate analyses given the known interaction between this pathway and dioxin and its potential role in diseases like cancer." (PMID 33849548, 2021). "Thus, unlike the Rac1/Cdc42 signaling pathway functioning in epithelial cells, the disruption of the Golgi apparatus trafficking pathways would significantly disturb the collective cancer cell polarization." (PMID 33499191, 2021). "The modes of action of dominant-negative mutants of RhoA in cancers are not clear, but as there is an inverse relationship between RhoA signaling and Rac1 signaling, at least in some cell types it is possible that inhibition of the Rho-regulated pathway results in increased Rac1 signaling." (PMID 30544828, 2018). "Furthermore, the translational relevance of these findings was assessed from the standpoint of generating a signature based on the expression and/or activation status of Rac1, Bcl-2 and STAT3, which could have implications for stratifying cancers by disease severity and chemoresistance." (PMID 26430964, 2015). "Therefore, the involvement of Rac1 in cancer biology should not be a specific target for therapeutic intervention of tumor metastasis, but rather could be generally applicable to other cancer-associated behavior." (PMID 25991673, 2015). "Thus, the role of Rac1 as a pleiotropic regulator of multiple cellular functions, including actin cytoskeletal reorganisation, gene transcription, and cell migration, needs to be elucidated further to explain the mechanism of the NDV-Rac1 interaction in human cancer cells." (PMID 25243137, 2014). "Moreover, altering the balance of Rac1 to Rac1b expression and/or function towards Rac1b could represent a novel therapeutic approach in suppressing metastatic progression in PDAC and probably other carcinomas." (PMID 24378395, 2014). "Thus, Rac1 targeting can suppress migration and invasion of both SP and non-SP cancer cells." (PMID 21347385, 2011). "NETs‐DNA enhanced endogenous binding of ITGB4 to integrin‐linked kinase (ILK), a putative mediator of NETs‐driven cancer metastasis, leading to recruitment of β‐parvin, but not α‐parvin or PINCH, to mobilize the small GTPases RAC1 and CDC42." (PMID 37828611, 2023). "We recently previously discovered that TRAIL-R2, but not TRAIL-R1, is capable of mediating cancer progression, invasion, and metastasis by cancer cell-autonomous activation of MPD- Ras-related C3 botulinum toxin substrate 1 (Rac1) axis." (PMID 36195672, 2023). "Compared to healthy controls, RAC1 and RAC1B were found to be significantly overexpressed in the serum of NSCLC patients, independent of the cancer stage." (PMID 30621237, 2019). "Furthermore, to detect whether Rac1 is also required for TIPE2 TCM-mediated inhibition of angiogenesis, we examined the proliferation, migration and tube formation capacity of HUVECs treated with TCM derived from mock, wild type TIPE2, and mutant TIPE2 plasmid transfected cancer cells, respectively." (PMID 27556698, 2016).
cancer (continued). "The possible apoptotic pathways for anti-cancer effects of curcumin on cell signal transduction include PI3K, Akt, mTOR, ERK5, AP-1, TGF-β, Wnt, β-catenin, Shh, PAK1, Rac1, STAT3, PPARγ, EBPα, NLRP3 inflammasome, p38MAPK, Nrf2, Notch-1, AMPK, TLR-4, and MyD-88." (PMID 41149437, 2025). "Collectively, these findings indicate that the simultaneous overexpression of CBX3, RAC1 and EGFR could lead to a negative synergistic effect on cancer patient survival." (PMID 37633946, 2023). "Although a cross-talk between signaling from Arf6, ERK and Rac1 may occur in different cellular processes, the precise molecular mechanisms implicating GEP100 in cancer cell motility have not yet been unraveled." (PMID 22701712, 2012).
tumor (712 papers, 2002 to 2026). "RAC1 expression was linked to genomic alterations, immune checkpoint activity, and reduced B cell infiltration, suggesting its role in shaping the tumor microenvironment." (PMID 39898257, 2025). "It has been reported that significant associations were observed between RAC1 and DNA methylation, immune cell infiltration, immune-related genes, tumor mutational burden, and microsatellite instability in most tumors." (PMID 40904408, 2025). "Multiomics integration highlighted RAC1 as a key risk gene, which was further examined using single‐cell and spatial transcriptomics (ST) to characterize expression patterns, tumor microenvironment interactions, and pathway enrichments." (PMID 41498044, 2025). "In hMM, wild-type and mutated RAC1 act as oncoproteins by promoting tumor cell proliferation, survival, and motility." (PMID 40724880, 2025). "In PANC-1 cells, treatment with TGF-β1 or, surprisingly, BMP-7 downregulated ECAD and another epithelial marker, RAC1b (a tumor-associated splice isoform of human RAC1)." (PMID 39682758, 2024). "RAC1B expression keeps RAC1 signalling pathways activated, including the tumour-associated signalling pathways, and enhances transcription, cell–cell adhesion, cell invasiveness and motility." (PMID 40396280, 2024). "In this regard, in our recent study, we also found that expressing activated RAC1 completely restored the sphere formation and tumor formation ability lost due to loss-of-RAB4A." (PMID 39463384, 2024). "RAC1 gain-of-function mutations have been reported to increase tumours resistance to chemotherapy, chemo-radiation, targeted therapy and anti-hormonal therapy." (PMID 40396280, 2024). "We have previously observed that depletion of the cell adhesion receptor JAM-A in tumor cells results in a loss of CIL associated with high Rac1 activity at sites of cell-cell contacts between colliding cells." (PMID 39086660, 2024). "Significantly, we have validated the overexpression of GTP-bound Rac1 in human tumor samples harboring the CGN c.3560C > T variant." (PMID 38424547, 2024). "Taken together, our results reveal that RAC signaling is required for the self-renewal maintenance of BCSCs in vitro, and that loss-of Rac1 function delays or suppresses breast tumorigenesis in a dose-dependent manner in vivo." (PMID 36599922, 2023). "Among the CNVs acquired in the second lesion, RAC1 amplification was reported in the tumor sample of patient #1, who already harboring a pathogenic mutation (p.Pro29Ser) in the same gene." (PMID 36901733, 2023). "RAC1 was reported to serve as an independent tumor diagnostic biomarker and survival predictor, and knockdown of RAC1 exerted suppressive effect on epithelial-mesenchymal transition in GC cells." (PMID 38154092, 2023). "A significant correlation between high RAC1 activity in clinical specimens and the worse survival of patients after surgery was associated with high metastasis and tumor chemoresistance." (PMID 36354566, 2022). "The tumor-related studies showed that Rac1 was associated with the occurrence, invasion, apoptosis, and cardiovascular formation of a few tumors." (PMID 35847360, 2022). "The potential mechanism underlying Nectin-4 in promoting the tumor cells growth, proliferation, and movement was confirmed by regulating Ras-related C3 botulinum toxin substrate 1 (Rac1) signaling activity." (PMID 35953862, 2022). "The increase of Rac1 activity or expression caused by gene mutation or other factors can promote the occurrence, development, metastasis, and invasion of tumor, resulting in poor prognosis of patients." (PMID 35847360, 2022). "Many studies have shown that Rac1 is over-expressed and mutated mutations in various tumors, which is an important reason for the abnormal tumor proliferation and metastasis." (PMID 35031595, 2022). "Dysregulation of activity of both Rac1 and RhoA has been linked to mesenchymal tumor movement and invasive phenotypes in cancer." (PMID 35241781, 2022).
tumor (continued). "We found that Rac1 mRNA levels are upregulated compared to normal tissue, correlate with tumor grade, and higher expression levels are associated with a poor survival expectancy, as seen with other solid tumors." (PMID 36230732, 2022). "These differential effects of Rac1 inhibition were related to the mutation and overexpression of Rac1 in tumor cells." (PMID 35031595, 2022). "Knockdown of RAC1 or inhibition of its expression was previously linked to decreased tumor cell growth, invasion and chemoresistance." (PMID 34803511, 2021). "RAC1 signaling is also involved in angiogenesis and required for vertical blood vessel sprouting associated with tumor-induced angiogenesis." (PMID 34827551, 2021). "Investigations of ras-related C3 botulinum toxin substrate 1 (RAC1) mutations through in silico approaches revealed that the pathogenic point mutation P29S would facilitate the design of tumour-targeting treatments." (PMID 34404882, 2021). "In mixed-breed dogs’ high tumor proliferation index was associated with the overexpression of RAC1, EGFR and VEGF-B, and moderate and strong correlations were found between PI and FLT1, EGFR and VEGF-B." (PMID 34679042, 2021). "In the present study, through whole-exome sequencing (WES), we identified the clonal acquisition of a novel RAC1 (P34R) mutation in the recurrent tumor of a PTC patient (BRAFT599del;K601N) that progressed under dabrafenib treatment." (PMID 34638434, 2021). "Intracellular mature IL-37 (amino acids 46-218) effectively inhibits the migration of multiple tumor cell types through the inhibition of Rac1 activation; thus, IL-37 loss or decreased expression in lung adenocarcinoma tissues results in tumor metastasis." (PMID 34248996, 2021). "Activated RAC1 (amplification/overexpression/GOF mutation) contributes to tumor progression and the development of resistance in different organ types of solid tumors." (PMID 32545340, 2020). "Over time, continuous high expressing of RAS (G12V) with subsequent slow stimulating of Rac1 causes extreme vacuolation of tumor cells, eventually leading to methuosis." (PMID 33542897, 2020). "In turn, increased PTBP1 levels induce a shift in the AS of tumor-associated transcripts, namely, the small GTPase Ras-related C3 botulinum toxin substrate 1 (RAC1), adaptor protein NUMB, and PKM." (PMID 33261131, 2020). "Considering that the GAP domain was reported to inactive Rac1 or Cdc42, which is involved in tumor cell migration and associated with MMPs, we detected the Rac1 and Cdc42 activity and MMP-2/9 expression level upon Porf-2 expression." (PMID 32676454, 2020). "Survival analyses demonstrated differences in the expression profile of investigated Rac1 while a higher level of studied GTPase was associated with poor prognosis linked with early tumor recurrence in patients." (PMID 32443784, 2020). "RAC1 has been found to be overexpressed in various tumors, and is closely associated with tumor migration, invasion and poor prognosis of carcinomas." (PMID 32411607, 2020). "In this concern, Rac1 transcripts are direct target of miR-320a (a tumor suppressor miRNA), whose expression is inversely associated with CRC and cell line aggressiveness." (PMID 32178475, 2020). "The HACE1 gene, localized to human chromosome 6q21, encodes the HACE1 HECT E3 ligase, a tumor suppressor in diverse tumors that acts in part by targeting the activated form of RAC1 GTPase for proteasomal degradation." (PMID 30622235, 2019). "RAC1 is involved in angiogenesis and required for vascular integrity and the sprouting blood vessels (associated with tumor-induced angiogenesis), as demonstrated in a conditional RAC1 knockout mouse model." (PMID 31027363, 2019). "In a mouse model of oncogenic Kras(G12D)-induced PDAC, Rac1 was required for early metaplastic changes and neoplasia-associated actin rearrangements in development of pancreatic cancer." (PMID 31817229, 2019).
tumor (continued). "Rac1 is also associated with angiogenesis, as injection of siRac1 into Neuro2a tumors in mice resulted in almost complete inhibition of tumor growth, correlated with reduced angiogenesis into the tumor." (PMID 31174284, 2019). "Aberrant activation of RAC1 is implicated in numerous aspects of tumor development and progression and is the subject of several recent peer-reviewed articles." (PMID 31027363, 2019). "Previously, it was reported that tumor mechanisms of primary resistance include mutations in RAC1, loss of PTEN, and copy number increase of CCND1, while secondary resistance mechanisms include alternative expression of BRAF and PI3K." (PMID 30885146, 2019). "Rac-1 is implicated in OC cell survival, tumor angiogenesis, resistance to therapeutics, and contribution to extraperitoneal dissemination." (PMID 31652539, 2019). "This endocytic trafficking route of active Rac1 through Rab5- and Arf6- positive compartments was linked to cell motility in a variety of tumor cells." (PMID 31766364, 2019). "While HACE1 has multiple targets, it has been shown that loss of HACE1 increases Rac1 activity, which induces reactive oxygen species generation and cell migration that likely contribute to Rac-mediated tumor progression." (PMID 30544910, 2018). "Rac1 has been shown to be an essential component of EGF receptor signaling in different tumor types and implicated in EGF receptor driven tumorigenesis." (PMID 30261690, 2018). "Univariate analysis showed that β1 integrin and Rac1 overexpression was associated with tumor cell polarity reversal, presence of LNM, and decreased DFS in IMPC patients." (PMID 29435106, 2018). "In contrast to tumor suppressor genes, where truncating mutations are prevalent and cause loss of function, the Rac1 mutations are like those in the oncoprotein Ras." (PMID 30261690, 2018). "Aberrant activation of Rac1 is implicated in numerous aspects of tumor development and progression and is the subject of several recent reviews." (PMID 30261690, 2018). "This complex phosphorylates a fraction of paxillin specifically associated with the cell membrane, and promotes Rac1 activation, thereby triggering membrane ruffling and cell invasion in both normal fibroblasts and tumor cells." (PMID 30459815, 2018). "There were also indications that these active mutants of RhoA and Rac1 can cause tumor growth in nude mice." (PMID 30544828, 2018). "Several classical molecules associated with tumor invasiveness, such as MMPs and uPA, have been demonstrated to be the downstream effectors of Rac1 signaling." (PMID 30534358, 2018). "Whole exome sequencing data from 74 tumor and normal sample pairs also identified Rac1 P29S as an activating mutation in head and neck squamous cell carcinoma." (PMID 27442895, 2017). "The antagonistic relationship between RAC1 and RAC1b perturbs the regulatory circuitry that controls actin cytoskeleton dynamics thereby leading to tumor-linked alterations in cell morphology and motility." (PMID 28499439, 2017). "Analyzing 10,000 tumor exomes, we identify more than 3000 rarely mutated residues in proteins as potentially functional and experimentally validate several in RAC1 and MAP2K1." (PMID 28115009, 2017). "Our study demonstrates for the first time that beta-catenin-RAC1 cascade signals integrin-directed metastasis-associated tumor cell phenotypes in TNBC." (PMID 27902969, 2017). "For instance, it has been shown that splicing pattern of Ron and Rac1 genes were altered in tumors and overexpression of their tumor-associated isoforms was sufficient to culture cell transformation." (PMID 28105922, 2016). "This complex phosphorylates a fraction of paxillin specifically associated to the cell membrane, and promotes Rac1 activation, thereby triggering membrane ruffling and cell invasion in both normal fibroblasts and tumour cells." (PMID 27181366, 2016).